CHPT1 (choline phosphotransferase 1)
Description:
Catalyzes the final step of de novo phosphatidylcholine (PC) synthesis, i.e. the transfer of choline phosphate from CDP-choline to the free hydroxyl of a diacylglycerol (DAG), producing a PC. It thereby plays a central role in the formation and maintenance of vesicular membranes.
Synonyms: CPT1; CPT
Tractability: Antibody: UniProt predicts a signal peptide or a membrane-spanning region. PROTAC: ubiquitination databases record sites on it; its protein half-life has been measured.
Gene: Protein-coding gene on chromosome 12 (101,696,947 to 101,744,140, forward strand). Ensembl gene ENSG00000111666.
Subcellular location: Golgi apparatus membrane
Subcellular location (Human Protein Atlas): Vesicles
Pathways (Reactome):
Metabolism: Synthesis of PC
Gene Ontology:
Molecular function: diacylglycerol cholinephosphotransferase activity; protein binding; diacylglycerol binding; phosphotransferase activity, for other substituted phosphate groups
Biological process: phosphatidylcholine biosynthetic process; platelet activating factor biosynthetic process; CDP-choline pathway; lipid metabolic process; regulation of cell growth; phospholipid biosynthetic process
Cellular component: Golgi membrane; endoplasmic reticulum membrane; Golgi apparatus; intracellular membrane-bounded organelle; membrane; cytoplasm; endomembrane system
Genetic constraint (gnomAD): Loss-of-function variants: 14 observed, 15.69 expected, observed/expected ratio (o/e) 0.89, 90% interval 0.59 to 1.39. The synonymous counts are far from expectation, so gnomAD's model fits this gene poorly and the ratio says little. Missense variants: 252 observed, 209.85 expected, observed/expected ratio (o/e) 1.2, 90% interval 1.08 to 1.33. Synonymous variants: 125 observed, 80.87 expected, observed/expected ratio (o/e) 1.55, 90% interval 1.34 to 1.79.
Homologues: Orthologues: chimpanzee CHPT1 (99% identical), pig CHPT1 (91% identical), mouse Chpt1 (89% identical), dog CHPT1 (88% identical), macaque CHPT1 (87% identical), rat Chpt1 (86% identical), guinea pig CHPT1 (83% identical), tropical clawed frog chpt1 (62% identical), zebrafish chpt1 (60% identical), Drosophila melanogaster bbc (50% identical), Caenorhabditis elegans cept-1 (44% identical), Caenorhabditis elegans cept-2 (40% identical). Paralogues in human: CEPT1 (61% identical), SELENOI (25% identical).
Diseases named in the same sentence as CHPT1 in open-access papers:
CHPT1 is named in the same sentence as 20 diseases in open-access papers, as found by Europe PMC text mining. Sharing a sentence is not in itself a finding about the gene and the disease. The quoted sentences say what the papers report.
breast carcinoma (9 papers, 2020 to 2025). "The predicted change of expression is in agreement with Pancan data on breast cancer patients that show the alternative allele of this variant to be associated with higher expression levels of CHPT1 gene (source: PancanQTL53, beta = 0.17)." (PMID 38862711, 2024). "On the other hand, some studies have shown that the downregulation of CHPT1 is associated with an unfavorable prognosis in certain types of solid tumors, such as breast cancer and lung cancer." (PMID 37629695, 2023). "It is important to note that CHPT1 gene is a direct target of estrogen (ERα binds its promoter upon estrogen treatment) and its inhibition is linked to decreased growth and cell proliferation in breast cancer cells." (PMID 38862711, 2024). "Clinically, CHPT1 expression in breast cancer is associated with a poor prognosis." (PMID 36879264, 2023). "CHPT1 also plays a role in the invasion of tamoxifen-resistant breast cancer cells, with tamoxifen-resistant LCC2 cells exhibiting greater invasiveness than tamoxifen-sensitive MCF7 cells under CHPT1 expression." (PMID 39746051, 2025). "To date, some lncRNAs have been reported to be associated with breast cancer, for instance, AGAP2-AS1 (AGAP2 antisense RNA 1) promoted breast cancer stemness and trastuzumab resistance by controlling choline phosphotransferase 1-meidiated fatty acid oxidation." (PMID 37036576, 2023). "Mounting evidence shows that CHPT1 is a curative target for prostate cancer and is related to stemness and trastuzumab resistance in breast cancer." (PMID 34925508, 2021). "CHPT1 mediates metabolic changes in breast cancer cells, and silencing CHPT1 can inhibit breast cancer cell proliferation and early metastasis of tamoxifen-resistant breast cancer cells, suggesting that CHPT1 is a treatment target for cancers." (PMID 33024640, 2020). "Additionally, immunohistochemical (IHC) analysis showed that the expression of CHPT1 is higher in breast cancer cells than in normal breast tissue and is higher in ER-positive than in ER-negative breast cancer." (PMID 39746051, 2025). "This environment of minimal residual disease (MRD) may function similarly to tamoxifen-resistant breast cancer cells, potentially increasing CHPT1 activity." (PMID 39746051, 2025). "Knockdown of CHPT1 inhibits the growth and proliferation of breast cancer cells, and in vivo experiments have shown that knockdown of CHPT1 inhibits the early metastasis of breast cancer cells." (PMID 35774129, 2022).
lung carcinoma (2 papers, 2021 to 2023). "Elevated biosynthesis of PE in lung cancer tissue was supported by enhanced expression of the PE biosynthesis genes ETNK2 and EPT1 and decreased expression of the PC and PI biosynthesis genes CHPT1 and CDS2, respectively, in different subtypes of lung cancer in publicly available datasets." (PMID 33408336, 2021).
prostate carcinoma (2 papers, 2021). A carcinoma that arises from epithelial cells of the prostate gland. "In prostate cancer cells that are resistant to enzalutamide, the enhancer element in CHPT1 SE transcribes lncRNA, namely eRNA, binds to BRD4, and regulates CHPT1 SE activity and CHPT1 expression, mediating androgen-independent drug tolerance." (PMID 34011395, 2021).
acute monocytic leukemia (1 paper, 2025). Acute monoblastic leukemia (AML-M5), is one of the most common subtypes of acute myeloid leukemia (AML) that is either comprised of more than 80% of monoblasts (AML-M5a) or 30-80% monoblasts with (pro)monocytic differentiation (AML-M5b). "Given the pivotal role of macrophages in the immune responses to both T2DM and TB, we employed a human acute monocytic leukemia cell (THP-1) model to investigate the regulatory effects of the cross-talk genes CHPT1, SERPING1, and CYP1B1 in inflammatory responses." (PMID 40917351, 2025).
depression (1 paper, 2025). "However, the role of CHPT1 in pain and depression is yet to be elucidated." (PMID 39545479, 2025). "CHPT1 has also been found to be upregulated in patients with ovarian cancer with concurring depression but not in patients without depression." (PMID 39545479, 2025).
lipid metabolism disorder (1 paper, 2022). "The protein–protein interaction was further analyzed, and the targets of PPAP2C, CHPT1, PPAP2B, PLD2 and PLD1 with higher degrees in the PPI network could be the key targets for preventing and treating the lipid metabolism disorder induced by CRE infection." (PMID 36295794, 2022).
mesothelioma (1 paper, 2025). A usually malignant and aggressive neoplasm of the mesothelium which is often associated with exposure to asbestos. "Subsequently, ChIP assays revealed increased recruitment of p65 to the NF-κB enhancers of CCTα, CHPT1, and CEPT1 in mesothelioma cell lines compared to normal mesothelial cells (HMC35)." (PMID 40016284, 2025). "Given the elevated mRNA expression of phospholipid biosynthesis genes (CCTα, CHPT1, and CEPT1) in mesothelioma cell lines, we investigated the putative regulatory role of NF-κB." (PMID 40016284, 2025).
cancer (4 papers, 2020 to 2025). A tumor composed of atypical neoplastic, often pleomorphic cells that invade other tissues. "In the future, the CHPT1-associated signaling pathway may be targeted in MSI cancer treatment." (PMID 36879264, 2023). "In addition, CHPT1, AHCYL1, and CHKB have been demonstrated to be associated with roles that lead to other cancers and affect patient outcomes, although relevant studies are scarce in BC." (PMID 38239641, 2023).
tumor (2 papers, 2020 to 2022). "CHPT1, which is responsible for the last step of de novo biosynthesis of PtdC, has been shown to be overexpressed in some tumours, and its overexpression positively correlates with tumour growth." (PMID 35215499, 2022).
CHPT1 also shares sentences with these, for which no sentence is quoted: diabetes (2 papers); colorectal cancer (1); infection (1); Insulin resistance (1); nonalcoholic fatty liver disease (1); ovarian carcinoma (1); Parkinson disease (1); Sepsis (1); spondylometaphyseal dysplasia (1); Stroke (1); type 2 diabetes (1).